METTL3 (methyltransferase 3, N6-adenosine-methyltransferase complex catalytic subunit)
Diseases named in the same sentence as METTL3 in open-access papers (continued):
Sharing a sentence is not in itself a finding about the gene and the disease.
osteoarthritis (25 papers, 2020 to 2025). A noninflammatory degenerative joint disease occurring chiefly in older persons, characterized by degeneration of the articular cartilage, hypertrophy of bone at the margins and changes in the synovial membrane. "Synovium-targeted METTL3 siRNA downregulates senescence-associated secretory phenotype expression and increases autophagy in osteoarthritis-fibroblast-like synoviocytes, further alleviating cellular senescence in joints and destabilization of the medial meniscus-induced cartilage destruction." (PMID 38553562, 2024). "In conclusion, in the model of osteoarthritis cartilage injury, METTL3-mediated m6A modification decreases PRDX3 mRNA stability." (PMID 40757971, 2025). "Targeting METTL3 is thus a potentially effective therapeutic strategy for patients with osteoarthritis cartilage injury." (PMID 40757971, 2025). "Targeting METTL3 or PRDX3 is thus a potentially effective therapeutic strategy for patients with osteoarthritis cartilage injury." (PMID 40757971, 2025). "Subsequently, the molecular mechanism by which METTL3 mediates ferroptosis in osteoarthritis through PRDX3 was investigated." (PMID 40757971, 2025). "Two clinical articles also revealed increased expressions of METTL3 mRNA and protein in cartilage of patients with osteoarthritis by using RT-PCR and Western blot." (PMID 38665846, 2024). "According to data from GSE117999, GSE98918, GSE29746, GSE55457, and GSE82107, translation of METTL3 was down-regulated in cartilage, meniscus, and synovial tissues of patients with osteoarthritis in comparison with the normal control." (PMID 38665846, 2024). "METTL3 has a functional role in mediating osteoarthritis progression by regulating NF-κB signaling and extracellular matrix (ECM) synthesis in chondrocytes." (PMID 36777725, 2023). "Some studies have shown that METTL3 dysfunction can lead to a variety of diseases, such as polycystic kidney disease, osteoarthritis, and chondropathy." (PMID 37644500, 2023). "METTL3 is an m6A methyltransferase that can accelerate aging and osteoarthritis progression by regulating autophagy." (PMID 36585683, 2022). "Previous studies have indicated that METTL3 plays a significant role in the pathogenesis of osteoarthritis." (PMID 36505479, 2022). "In osteoarthritis, METTL3 remarkably decreased the stability of PRDX3 mRNA." (PMID 40757971, 2025). "Moreover, METTL3-mediated m6A modification decreases PRDX3 mRNA stability by YTHDF1 in the osteoarthritis cartilage injury model." (PMID 40757971, 2025). "Although METTL3 may help the chondrogenesis of BMSCs, the role of this m6A “writer” in the development of osteoarthritis was debatable." (PMID 38665846, 2024). "It has also been further confirmed that the expression of the m6A methylated gene METTL3 is decreased in osteoarthritis and may be involved in osteoarthritis by regulating inflammatory responses." (PMID 36777725, 2023). "In addition, a study on osteoarthritis showed that the silencing of METTL3 suppressed IL-1β-induced inflammatory cytokines and the NF-κB signaling pathway in chondrocytes." (PMID 36293529, 2022). "There are no related researches about CBLL1 in cytokine signalling and immune regulations, but it has been reported METTL3 depletion enhanced proinflammatory cytokine expression in osteoblast and METTL3 promotes cytokine inflammatory response of osteoarthritis." (PMID 33724691, 2021). "Their results indicated that METTL3 may play a functional role in osteoarthritis by regulating the nuclear factor κB signalling pathway, extracellular matrix synthesis and metabolism in chondrocytes." (PMID 33098220, 2020). "A similar phenomenon was found in a recent study where METTL3 regulated autophagy by affecting the stability of ATG7 transcripts in a m6A-dependent manner, thereby affecting synovial cell senescence in osteoarthritis." (PMID 39893158, 2025).
osteoarthritis (continued). "Extracellular vesicles derived from human umbilical MSCs interact with METTL3 to reduce NLRP3 m6A levels in macrophages, alleviating osteoarthritis in mouse models." (PMID 40502627, 2025). "Methyltransferase-like 3 (METTL3)-mediated M6A can attenuate Atg7 mRNA stability, decreasing its expression and facilitating cellular aging and osteoarthritis by regulating the autophagy-GATA4 axis." (PMID 38553562, 2024). "In osteoarthritis patients, the mRNA expression of PRDX3 was negatively correlated with METTL3 mRNA expression, but not with METTL14 mRNA expression." (PMID 40757971, 2025).
rheumatoid arthritis (25 papers, 2019 to 2025). A chronic, systemic autoimmune disorder characterized by inflammation in the synovial membranes and articular surfaces. "In rheumatoid arthritis, lipopolysaccharides can lead to increased levels of METTL3 expression as well as bioactivity in the macrophages; METTL3 overexpression can suppress the inflammatory response caused by the NF-κB pathway." (PMID 37854284, 2023). "However, little is known of the role and underlying mechanism of METTL3 in rheumatoid arthritis (RA)." (PMID 31772500, 2019). "It is investigated that in condition of rheumatoid arthritis METTL3 governs the homeostasis and differentiation of T cells by targeting the IL-7/STAT5/SOCS signal axis and regulates the stability of Treg cells via targeting the IL-2/STAT5/SOCS pathway." (PMID 39717780, 2024). "METTL3, the primary enzyme responsible for m6A methylation modification, plays a crucial role in immune and inflammatory regulation in rheumatoid arthritis (RA)." (PMID 39199429, 2024). "It has been reported that the expression of METTL3 is significantly increased in patients with rheumatoid arthritis, affecting the secretion of inflammatory cytokines through the NF-κB pathway." (PMID 35480327, 2022). "METTL3 expression is significantly upregulated in blood samples from patients with rheumatoid arthritis." (PMID 34395520, 2021). "It has been reported that METTL3 may promote inflammatory response via the NF-κB signaling pathway, which exerts a significant impact on the occurrence and development of rheumatoid arthritis 36,37." (PMID 38725850, 2024). "In fibroblast-like synoviocytes, which exert a crucial effect on the occurrence and development of rheumatoid arthritis, METTL3 may promote fibroblast-like synoviocyte activation and inflammatory response via the NF-κB signaling pathway." (PMID 35165276, 2022). "Additionally, by inducing apoptosis of RA‐FLS, METTL3 contributes to rheumatoid arthritis." (PMID 41316520, 2025). "It has been reported that METTL3 expression is elevated in peripheral blood mononuclear cells from rheumatoid arthritis (RA) patients, as well as in LPS-stimulated macrophage-like cells (pTHP-1)." (PMID 36674918, 2023). "Moreover, some studies found that polymorphisms of METTL3 and fat mass and obesity associated (FTO) genes are involved in the pathogenesis of some autoimmune diseases, such as rheumatoid arthritis (RA) and latent autoimmune diabetes (LADA)." (PMID 34616359, 2021). "In vitro and in vivo experiments using samples from patients with rheumatoid arthritis (RA) revealed significantly elevated METTL3 levels in patients with RA that played an important role in LPS-induced inflammation in macrophages via the NF-κB signaling pathway." (PMID 34307373, 2021). "YTHDC2 and METTL3 jointly regulate the expression of adhesion molecule with Ig like domain 2 (AMIGO2), regulate the proliferation and invasion ability of rheumatoid arthritis synovial fibroblasts, and thereby affect the disease progression of rheumatoid arthritis." (PMID 38790013, 2024). "For example, global m6A and METTL3 expression levels have been shown to be significantly increased, while FTO, ALKBH5 and YTHDF2 mRNA levels have been shown to be significantly downregulated in rheumatoid arthritis (RA)." (PMID 36457997, 2022).
esophageal cancer (24 papers, 2020 to 2026). A primary or metastatic malignant neoplasm involving the esophagus. "In summary, this study suggests that METTL3 is not only a potential pathogenic molecule for esophageal carcinogenesis and progression but also a potential target for immunotherapy in esophageal cancer." (PMID 35574315, 2022). "In conclusion, IFIT2 and METTL3 may serve as targets for immunotherapy in addition to being potential pathogenic factors in esophageal cancer development." (PMID 36386128, 2022). "METTL3 correlates positively with myc mRNA expression, contributing to the malignant progression and immune evasion in esophageal cancer." (PMID 39791162, 2025). "METTL3, as a m6A writer, its deficiency can down-regulate the expression of EPPK1 and thereby inhibit the PI3K/AKT pathway, then curbing the development of esophageal cancer." (PMID 41256854, 2025). "Research has indicated that elvitegravir has the ability to suppress oesophageal cancer metastasis by increasing the proteasome degradation of the M6A methyltransferase METTL3." (PMID 38291427, 2024). "In esophageal cancer, METTL3 is also significantly overexpressed and can lead to mRNA degradation by upregulating the m6A level of APC mRNA and recruiting the m6A “reader” protein YTHDF2." (PMID 36830614, 2023). "METTL3 has also been confrimed to be highly expressed in ESCC and is associated with poor prognosis in esophageal cancer." (PMID 36733344, 2023). "A recent study has illuminated that via Notch signaling pathway METTL3-mediated m6A mRNA modification can propel esophageal cancer initiation and progression." (PMID 37313409, 2023). "ROC curve analysis showed that the risk model constructed by the expression and prognosis of IFIT2 and METTL3 in esophageal cancer patients was closely related to the prognosis survival of more than 3 years (AUC = 0.77)." (PMID 36386128, 2022). "To create a xenograft tumor model, we inoculated KYSE510 cells subcutaneously into BALB/c nude mice and discovered that sh-METTL3 inhibited the tumorigenicity of esophageal cancer KYSE510 cells in the nude mouse tumor model." (PMID 36386128, 2022). "In this study, we demonstrate that METTL3 regulates esophageal cancer proliferation, invasion, and immunity via the downstream target IFIT2." (PMID 36386128, 2022). "Our study shows that METTL3, a protein highly expressed in esophageal cancer tissues, can promote the proliferation, invasion and metastasis of esophageal cancer both in vitro and in vivo." (PMID 36386128, 2022). "In our study, a significant amount of METTL3 was detected in tissues from esophageal cancer patients compared to adjacent tissues." (PMID 36386128, 2022). "These immune genes were mostly linked with immune processes, such as cytokine receptors, the MAPK signaling pathway, and natural killer cell-mediated cytotoxicity, indicating that METTL3 is a key molecule in the immune regulation of esophageal cancer." (PMID 35574315, 2022). "Collectively, these results clearly demonstrated that METTL3 is highly expressed in esophageal cancer patients." (PMID 36386128, 2022). "Additionally, METTL3, FTO, ALKBH5, and IGF2BP2 are overexpressed in patients with esophageal cancer and closely linked to myc mRNA expression." (PMID 39791162, 2025). "In esophageal cancer, METTL3 mediates m6A modification in 3’UTR of TNFR1 mRNA." (PMID 36830614, 2023). "METTL3 could regulate esophageal cancer proliferation, invasion and immunity via the downstream target IFIT2." (PMID 37598390, 2023). "We then characterized the expression relationship of IFIT2 with METTL3 in esophageal cancer cells." (PMID 36386128, 2022). "METTL3 and IFIT2, which may serve as prognostic or diagnostic indicators for esophageal cancer, also offer fresh evidence in favor of immunotherapy and customized treatment for ESCC patients." (PMID 36386128, 2022). "However, it is still unclear how METTL3 contributes to esophageal cancer and what its exact mechanism is." (PMID 36386128, 2022).
esophageal cancer (continued). "The METTL3 downstream target gene IFIT2 was identified in esophageal cancer cells using MeRIP-seq." (PMID 36386128, 2022). "For instance, MALAT1-m6A modifications generated by the METTL3-METTL14 complex are important to the metastatic ability of esophageal cancer cells (ESCCs), but silencing METTL3 cannot recapitulate the phenotypes of impaired migration observed in MALAT1-Δm6A cells." (PMID 34315512, 2021). "In EC, the expression of METTL3 is related to recurrence, suggesting that METTL3 overexpression may be a key factor in the resistance to platinum drugs in patients with esophageal cancer." (PMID 34246319, 2021). "We also investigated whether METTL3’s role in esophageal cancer is immune-related." (PMID 36386128, 2022). "In our current study, employing a pan-cancer analytical approach, we developed METTL3 and METTL14 knockdown EC109 esophageal cancer cell lines to explore the impact of gene silencing on cellular proliferation." (PMID 38965238, 2024). "To further investigate the relationship between METTL3 and IFIT2 in the tumorigenesis of esophageal cancer, we knocked down IFIT2 in KYSE150 cells, accompanied by METTL3 knockdown." (PMID 36386128, 2022). "This study sought to analyze the regulatory mechanism of METTL3 in epithelial-mesenchymal transition (EMT), invasion, and metastasis in esophageal cancer (ESCA)." (PMID 34666602, 2021). "Then, ELISA result showed that METTL3 and METTL14 were highly expressed in esophageal cancer, whereas FTO and ALKBH5 expressed lowly in esophageal cancer." (PMID 33596916, 2021). "In summary, METTL3 and METTL3- mediated m6A modifications have been shown to enhance radioresistance by increasing the expression of DNA repair proteins in GBM and cervical and esophageal cancers." (PMID 39972266, 2025). "Therefore, we investigated the correlation of METTL3 and IFIT2 expression with immune cells in esophageal cancer." (PMID 36386128, 2022). "Furthermore, our study indicated that although METTL3, METTL14, FTO and ALKHB5 differentially expressed in esophageal cancer patients’ tissues and normal esophageal tissues, only METTL3 expression was related to esophageal cancer recurrence." (PMID 33596916, 2021). "Additionally, the immune response during the development of esophageal cancer may be mediated by METTL3 and IFIT2, which would explain why patients with esophageal cancer have a poor prognosis." (PMID 36386128, 2022).
head and neck squamous cell carcinoma (24 papers, 2020 to 2026). A squamous cell carcinoma that arises from any of the following anatomic sites: lip and oral cavity, nasal cavity, paranasal sinuses, pharynx, larynx, and salivary glands. "In head and neck squamous cell carcinoma, METTL3 was significantly upregulated and negatively associated with clinical prognosis." (PMID 39711977, 2024). "METTL3-mediated m6A modification of CDC25B is upregulated in head and neck squamous cell carcinoma (HNSCC), and promotes HNSCC malignant characteristics, including cell proliferation, migration, and invasion, as well as angiogenesis." (PMID 39691597, 2024). "According to the Cancer Genome Atlas (TCGA) database, METTL3 expression is higher in head and neck squamous cell carcinoma (HNSCC) compared to normal tissue." (PMID 39822792, 2024). "Emerging studies have demonstrated the pivotal role of METTL3 in head and neck squamous cell carcinoma (HNSCC) and thyroid carcinoma (TC)." (PMID 33879256, 2021). "It has been reported that a low level of METTL3 increases the sensitivity of cancer cells to the treatment of DNA damage, while upregulated METTL3 reduces the survival rate of patients with head and neck squamous cell carcinoma who have received cisplatin or radiation treatment of DNA damage." (PMID 39054967, 2024). "To date, it was found that METTL3 overexpression promoted head and neck squamous cell carcinoma (HNSCC) cell proliferation, migration, invasion, and angiogenesis, while knockdown of METTL3 had the opposite effect in vivo and in vitro." (PMID 38966069, 2024). "Here, we aimed to explore the biological function and clinical significance of m6A modification and METTL3 in head and neck squamous cell carcinoma (HNSCC)." (PMID 35287752, 2022). "METTL3/14 enhance the migration of head and neck squamous cell carcinoma (HNSCC) by upregulating lncRNA activating regulator of DKK1 (LNCAROD)." (PMID 32767982, 2020). "Methyltransferase-like 3 (METTL3) serves as the main catalytic subunit of the m6A writer and plays a role in the progression of head and neck squamous cell carcinoma." (PMID 39822792, 2024). "Taken together, the m6A methyltransferase METTL3 plays a critical role in regulating tumor angiogenesis in various cancers, including GC, CRC, liver cancer, BCa, and head and neck squamous cell carcinoma." (PMID 39295872, 2024). "In head and neck squamous cell carcinoma (HNSCC), METTL3 and HNRNPC were highly expressed in tumor tissue than normal tissue, high expression of METTL3 and HNRNPC were positively associated with the infiltration of CD4 naive T cells, CD4 memory-activated T cells, and eosinophils." (PMID 35296338, 2022). "METTL3‐mediated and METTL14‐mediated m6A modification enhances the stability of LNCAROD in head and neck squamous cell carcinoma (HNSCC) cells, an effect that is associated with the high expression of LNCAROD in HNSCC." (PMID 34432955, 2021). "In head and neck squamous cell carcinoma (HNSCC) cells, the stability of LNCAROD is enhanced through the METTL3 and METTL14-mediated m6A modification." (PMID 33292652, 2020). "The lncRNA lnc-H2AFV-1 upregulates the expression of intraflagellar transport (IFT) 80 by regulating METTL3/14 and FTO in head and neck squamous cell carcinoma (HNSCC), thereby promoting cell growth." (PMID 38351139, 2024). "The co-action of METTL3 and METTL14 with m6A modification promotes the stability of lncRNA LNCAROD in head and neck squamous cell carcinoma (HNSCC)." (PMID 36561529, 2022). "METTL3/METTL14-induced m6A methylation stabilized LNCAROD in head and neck squamous cell carcinoma (HNSCC) tissue, which augmented malignant cell multiplication and invasion in vivo and in vitro." (PMID 36553003, 2022). "Likewise, METTL3- and METTL14-mediated m6A modification of LncAROD enhanced its stability and promoted ternary complex formation with HSPA1A and YBX1, driving progression in head and neck squamous cell carcinoma." (PMID 34458149, 2021).
head and neck squamous cell carcinoma (continued). "Similarly, LNCAROD is up-regulated by METTL3/METTL14 in head and neck squamous cell carcinoma (HNSCC) and impels its tumorigenicity through preventing YBX1 from degradation." (PMID 33754077, 2021).